SNHG1 (small nucleolar RNA host gene 1)
Diseases named in the same sentence as SNHG1 in open-access papers (continued):
Sharing a sentence is not in itself a finding about the gene and the disease.
SNHG1 also shares sentences with these, for which no sentence is quoted: renal cell carcinoma (4 papers); brain tumor (2); infarction (2); liver fibrosis (2); lung adenocarcinoma (2); pituitary tumor (2); adenocarcinoma (1); Bladder Urothelial Carcinoma (1); bone cancer (1); cardiac hypertrophy (1); cardiomyopathy (1); cardiovascular disorder (1); chondrosarcoma (1); Cognitive impairment (1); colorectal adenocarcinoma (1); cryptococcosis (1); laryngeal carcinoma (1); lentivirus infection (1); multiple sclerosis (1); Nephroblastoma (1); neurological disorders (1); neuropathic pain (1); neurotoxicity (1); pancreatic ductal adenocarcinoma (1); promyelocytic leukemia (1); Stroke (1); viral infection (1).